PRR11-AS1 (PRR11 antisense RNA 1)
Synonyms: AC099850.3; AC099850.4; lnc-SKA2-1; CTD-2510F5.4
Gene: Long non-coding RNA gene on chromosome 17 (59,202,677 to 59,203,829, reverse strand). Ensembl gene ENSG00000265415.
Diseases named in the same sentence as PRR11-AS1 in open-access papers:
PRR11-AS1 is named in the same sentence as 1 disease in open-access papers, as found by Europe PMC text mining. Sharing a sentence is not in itself a finding about the gene and the disease.
PRR11-AS1 shares sentences with these, for which no sentence is quoted: cancer (1 paper).